XBP1 (X-box binding protein 1)
Diseases named in the same sentence as XBP1 in open-access papers (continued):
Sharing a sentence is not in itself a finding about the gene and the disease.
tumor (continued). "Additionally, tumor growth in vivo was suppressed by the induction of LINC00963 overexpression, this effect of which could be mediated by miR-320a/XBP1." (PMID 34112145, 2021). "Therefore, a negative feedback loop between Fbw7 and XBP1 contributes to the regulation of tumor development and can be an attractive target for novel therapy in cancers." (PMID 30783083, 2019). "As a consequence, deregulation of the IRE1α-XBP1 axis has been reported to account for dysfunctional dendritic cells (DCs) and neutrophils, and CHOP is critical for the immune inhibitory activity of tumor-infiltrating myeloid-derived suppressor cells (MDSCs) and of CD8+ T cells." (PMID 31597321, 2019). "Based on our results, in ES, IRE1α-XBP1 inhibitors, especially toyocamycin, acceptably exert anti-tumor activity regardless of whether these tumors had a high or weak expression of XBP1s." (PMID 29581854, 2018). "Implantation of malignant cells or transformed fibroblasts lacking IRE1α/XBP1 or PERK/eIF2α in mice resulted in reduced tumor growth, which was attributed to low angiogenesis and increased sensitivity of the cancer cells to ER stress inducers, including hypoxia and high levels of ROS." (PMID 28105371, 2017). "This similarity may be sufficient as the tumor-suppressive properties of ire-1 described herein are independent of xbp-1." (PMID 26192965, 2015). "However, the role of ZFP36 and XBP1 in tumor angiogenesis has not yet been reported." (PMID 36246978, 2022). "Activation of XBP1-s by unsaturated aldehyde 4-hydroxy-trans-2-nonenal (4-HNE), a byproduct of lipid peroxidation, promotes the production of triglyceride and aberrant lipid accumulation in DCs, and subsequently, causes the failure of DCs to assist T cells in exerting their anti-tumor function." (PMID 35269888, 2022). "The CD138+CD3+ tumor cells also expressed high levels of IGHM, CD27, and XBP1, but were absent of CD19, CD22, CD24, and CD10 expression." (PMID 36494694, 2022). "The pathway score for spliced XBP1 (XBP1s) trended toward a mild negative correlation with CYT score and a positive correlation with SCNA (n = 18 tumor types with non‐zero pathway score)." (PMID 34698427, 2021). "Cell treated by specific inhibitors of the UPR downstream mediators or mice malignant cells lacking IRE1α, XBP-1, PERK, or ATF6 are more sensitive to hypoxia, with higher production of ROS, lower angiogenesis, delayed tumour progression and metastasis." (PMID 29415493, 2018). "Therefore, PERK-p-eIF2α is crucial for UPR-induced autophagy in intestinal cells following Xbp1 deficiency, and the absence of ATG7 leads to significant deterioration of intestinal inflammation, which could clearly, in a chronic manner, lead to the onset of tumor forms." (PMID 40723802, 2025). "Notably, in chondrosarcoma, only a single study reports that PRP-1 (proline-rich polypeptide), a toll-like receptor ligand, increases the expression of PERK, eIF2α, ATF4, CHOP, ATF6, IRE1α, and XBP1; however, no studies have yet investigated the functional role of the UPR in this tumor." (PMID 41228282, 2025).
cancer (220 papers, 2007 to 2026). A tumor composed of atypical neoplastic, often pleomorphic cells that invade other tissues. "The IRE1α/XBP1 branch is implicated in the development of a variety of hematologic and pancreatic cancers." (PMID 40650182, 2025). "Significant evidence demonstrates the pathogenic role of XBP1 in cancers and its utility as a therapeutic target." (PMID 40179083, 2025). "Activation of IRE1α via ER stress triggers the formation of the spliced form of XBP1 (XBP1s), which has been linked to a pro-survival effect in cancer cells." (PMID 35626128, 2022). "Spautin-1 prevented the induction of UPR-associated proteins, including glucose-regulated protein 78, activating transcription factor 4, and a splicing variant of x-box-binding protein-1, and showed preferential cytotoxicity in glucose-starved cancer cells." (PMID 35798783, 2022). "HCC biopsies from human patients showed elevated XBP1 expression levels, whereas cancer cells deficient in XBP1 are less prone to developing solid tumors in nude mice." (PMID 34671553, 2021). "In drug-resistant malignant tumors, XBP1 mRNA is continuously spliced, and XBP1 modulates a number of genes associated with angiogenesis, cell proliferation, and metastasis." (PMID 33947921, 2021). "X-box-binding protein 1 (XBP1) is generated through the activation of the IRE1α-mediated cleavage of XBP1 mRNA cleavage, which expression is associated with poor prognosis in cancer patients." (PMID 35222510, 2021). "Increased XBP1 splicing has been demonstrated in numerous cancers and is associated with more malignant phenotypes and poor survival." (PMID 33514437, 2021). "Especially, it has been reported that the active form of XBP1 derived from splicing of XBP1 mRNA is associated with cancer development." (PMID 30783083, 2019). "XBP1 contributes to the pathogenesis of multiple myeloma, and has been implicated in cancer cell de-differentiation, susceptibility to oncovirus infection and the epithelial-to-mesenchymal transition." (PMID 28105371, 2017). "Nevertheless, recent studies by Gabrilovich and colleagues have elegantly reinforced the crucial immunoregulatory role of aberrant IRE1α-XBP1 signaling in human cancer-associated myeloid cells." (PMID 28105371, 2017). "Since oxidative stress is an important stimulus for the activation of proteolytic systems and muscle wasting, it is possible that overstimulation of the IRE1α/XBP1 axis causes muscle wasting through augmenting fatty acid oxidation and oxidative stress during cancer cachexia." (PMID 40655023, 2025). "Notably, many studies have demonstrated that XBP1, which has a close association with tumorigenesis and progression, is involved in the intense competition for nutrients and metabolites between cancer cells and TILs in the TME." (PMID 36092910, 2022).
cancer (continued). "Importantly, to deeply comprehend the association between expression of XBP1 and immune regulation, relations between three kinds of immunomodulators and XBP1 expression were further analyzed across 30 cancer types." (PMID 35991556, 2022). "This loss of activity is in line with the observation that XBP1 expression is reduced in cancer." (PMID 33517887, 2021). "Additionally, XBP1 overexpression is closely associated with clinicopathological features and poor prognosis of multiple human cancers." (PMID 32793479, 2020). "Furthermore, XBP1 overexpression was associated with poor clinicopathological features and clinical outcomes of these cancers." (PMID 32793479, 2020). "This further suggest that overexpression of XBP1s may contribute to low level of Fbw7 expression, and low level of Fbw7 or dysfunction of Fbw7 by mutation may contribute to high level of XBP1 expression in human cancers." (PMID 30783083, 2019). "Several studies have revealed an association between the IRE1α-XBP1 pathway and human cancers." (PMID 29581854, 2018). "XBP1 seems to play a pivotal role in the pathogenesis of MM; its expression is often high in MM, and mutated XBP1 has been observed in MM and other cancer patients." (PMID 29783691, 2018). "XBP1-deficient cancer cells showed hypersensitivity to ER stress or hypoxia condition." (PMID 30081573, 2018). "IRE1α‐XBP1 activation induced by lipin‐1 deficiency could be considered as self‐protective response to keep intracellular homeostasis in cancer cells." (PMID 29659171, 2018). "Though the importance of XBP1 has been indicated by studies with various cancer cells, the detailed mechanism underlying the importance remains largely unknown." (PMID 26633383, 2015). "In addition to HNSC, high XBP1 expression also significantly increased the risk of death in two types of cancer patients (LGG, HR = 1.82; UVM, HR = 24.24) and reduced the risk of death in three types of cancer patients (OV, HR = 0.52; PCPG, HR = 0.17; SKCM, HR = 0.64)." (PMID 37627013, 2023). "Interestingly the main downstream effector of IRE1, XBP1 has also been found mutated in cancer." (PMID 32111004, 2020). "Therefore, XBP1 may be activated by combined metabolic stresses associated with the acquisition of cancer stem cell and TNBC properties." (PMID 25927911, 2014). "MYC has previously been identified as capable of binding to the XBP1 promoter and positively regulating expression in cancer models." (PMID 40721291, 2025). "Situated downstream of the cGAS-STING pathway, IRE1α-XBP1 expression has been shown to rescue cancer cells in B-cell malignancies from STING agonist-induced apoptosis." (PMID 41301006, 2025). "MKC-3946 enhances CHOP-mediated apoptosis and blocks XBP1 splicing induced by chemotherapeutic agents, making it a promising candidate for improving cancer treatment outcomes, particularly in MM." (PMID 41473415, 2025). "Dual inhibitors, such as MKC-3946 and GSK2850163, are also effective in cancer treatment by modulating kinase-driven XBP1 splicing and RNase-driven mRNA decay, offering therapeutic potential for chronic ER stress-related diseases." (PMID 41473415, 2025). "Although targeted ablation of the PERK arm of the UPR exacerbates cancer cachexia in mice, inhibition of XBP1, a downstream target of TLR‐MYD88 signalling and the IRE1α arm of the UPR ameliorated cancer‐induced muscle wasting." (PMID 39810606, 2025).
cancer (continued). "Snail is known to downregulate CDH1 and upregulate VIM, while XBP1 has been recently linked to EMT and metastasis, impacting cancer progression and therapy outcomes." (PMID 39759848, 2025). "Earlier work has shown that enzymatic inhibition of IRE1, either at the kinase or RNase level, or XBP1 disruption, can be efficacious in models representing diverse cancers." (PMID 40208872, 2025). "In cancers, the upregulation of IRE1α-XBP1 signaling has been proposed as a mechanism for relieving the ER stress associated with oncogene activation." (PMID 40005508, 2025). "There is growing evidence that XBP1 plays a significant role in cancer pathogenesis and can be used as a therapeutic target." (PMID 40179083, 2025). "In mice with colorectal cancer, upregulation of XBP1 activation in macrophages promotes cancer growth and metastasis." (PMID 40547943, 2025). "Given that XBP1 pre-mRNA negatively regulates sXBP1 activity, it is also possible that sXBP1 induces XBP1 expression as an attempt to inhibit its hyperactivation during cancer cachexia." (PMID 40655023, 2025). "This activation subsequently triggers the IRE1α–XBP1 axis, promoting the expression of PD‐L1 and the secretion of cancer cell‐promoting factors such as IL‐10, VEGF, IL‐6, and IL‐8." (PMID 40547943, 2025). "Collectively, these examples provide evidence of the druggability of the IRE1α-XBP1 axis, but the dosage and agent will likely depend on the cancer subtype and patient profile." (PMID 41301006, 2025). "The findings of the present study suggest a pivotal role of the IRE1α/XBP1 signaling in skeletal muscle wasting during cancer cachexia." (PMID 40655023, 2025). "In fact, mice with functional autophagy even displayed a tendency to develop more dedifferentiated carcinomas, as we found more high-grade adenocarcinomas in Xbp1/Rnaseh2bΔIEC mice compared to Atg16l1/Xbp1/Rnaseh2bΔIEC mice." (PMID 41057521, 2025). "Of the cancer related eGenes, XBP1 is relevant for different processes in tumors due to its role in unfolded protein response (UPR)." (PMID 39623312, 2024). "X box-binding protein-1 (XBP1) is a transcriptional factor that is activated upon unfolded protein accumulation and is essential for cancer cells to survive under hypoxic conditions." (PMID 39768226, 2024). "This new mechanism is in accordance with previous works showing that XBP-1(S) plays a key role in cancer cell survival under hypoxia." (PMID 36831485, 2023). "IRE1α-XBP1 signaling is emerging as a central orchestrator of malignant progression and immunosuppression in various cancer types." (PMID 36624093, 2023). "Although this observation is not surprising due to the direct involvement of RtcB ligation activity on XBP1, it highlights the potential of RtcB as a therapeutic target especially in cancer." (PMID 37935993, 2023). "The expression of ADORA2A and XBP1 was found to have a significant impact on the survival of most cancer types." (PMID 37627013, 2023). "Deregulation of IRE1 signaling, including overactivation of XBP1 splicing, has been reported as promoting proliferation of several cancer types, including glioblastoma, breast, prostate, and pancreas." (PMID 37721642, 2023). "Toyocamycin (Toy), as a promising anti-cancer drug, can prevent IRE1α splicing X-box binding protein 1 (XBP1u) to effectively inhibit the survival of cancer cells." (PMID 37064867, 2023). "XBP1 exerts various functions for cancer development, such as promoting cell proliferation, migration, and invasion, and inhibits cell apoptosis or autophagy." (PMID 36979962, 2023). "The IRE1α-XBP1 arm of the unfolded protein response (UPR) has been associated with immunosuppression and cancer progression." (PMID 36624093, 2023). "Since XBP1 splicing has a prosurvival output, which is often overactive in cancer, it remains a promising target." (PMID 37721642, 2023).
cancer (continued). "In the present study, XBP1 expression was the highest in BC across human cancers, and the mRNA and protein levels of XBP1 in BC were higher than that in normal tissue." (PMID 35543228, 2022). "We found that SpiD7 selectively induced caspase-mediated apoptosis in cancer cells, whereas normal cells exhibited robust XBP1 splicing, indicating adaptation to stress." (PMID 35378132, 2022). "MYC-driven cancer cells were found to be highly dependent on IRE1α/XBP1 and exquisitely sensitive to pharmacological inhibition of IRE1α." (PMID 35349489, 2022). "Our data establish a previously unappreciated role of FOXK2 in regulating cancer stemness through fine-tuning the intracellular stress defense mechanism governed by IRE1α/XBP1." (PMID 35349489, 2022). "The IRE1α–XBP1 axis is also needed for the survival of this cancer type, as inhibition of the axis led to induction of apoptosis in PEL cells." (PMID 35626128, 2022). "IRE1-XBP1(X-box binding protein 1) signaling is involved in the reprogramming of cancer metabolism during endoplasmic reticulum stress." (PMID 36092873, 2022). "XBP-1 s has been reported to be widely expressed in cancers, such as multiple myeloma, hepatocellular carcinoma, and CRC." (PMID 34521445, 2021). "Following 8 h of co-culture, compared with the sgCon TAMs, the RFP-labeled cancer cells (red) were efficiently phagocytosed by sgXBP1 hiTAMs or sgXbp1 miTAMs, indicating that XBP1 knockout increased the phagocytic capacity of TAMs remarkably." (PMID 34667145, 2021). "Cancerous lesions had more infiltration of XBP1+CD68+ cells (white) compared to normal tissue (14.11 ± 1.10 vs. 3.40 ± 0.18; P < 0.0001), XBP1+CD206+ macrophages displayed the similar pattern (3.26 ± 0.37 vs. 1.07 ± 0.15; P < 0.0001)." (PMID 34667145, 2021). "XBP1 has been reported be a potent oncogenic protein in the process of tumorigenesis and metastasis in various cancers via various signal pathway." (PMID 34094948, 2021). "In response to chronic stress, many cancer cells activate the UPR through the IRE1α–XBP1 pathway in order to survive." (PMID 34663798, 2021). "Noteworthily, IRE1α-XBP1 pathway has also been reported to be partly responsible for the induction of autophagy in cancer." (PMID 34112145, 2021). "Reverse transcriptase PCR (RT-PCR) results indicated that XBP1 mRNA splicing in TAMs was increased compared with that in PBMs and cancer cells." (PMID 34667145, 2021). "Quantitative analyses consistently confirmed that the expression level of spliced XBP1 mRNA in hTAMs was increased in hTAMs compared with that in control PBMs and cancer cells." (PMID 34667145, 2021). "Over-expression of XBP1 accelerates cancer cell invasion, suppressed by knockout of XBP1 using small interfering RNA (siRNA)." (PMID 33514437, 2021). "This novel IRE1α/XBP1/MYC axis in NK cells provided a new insight for host protection against NK cell-sensitive cancer." (PMID 33267910, 2020). "XBP1 presents overexpressed in various certain human cancer tissues and plays an oncogenic role in carcinogenesis and progression." (PMID 32793479, 2020). "With regard to muscle wasting, activation of the UPR has been shown to contribute to cancer cachexia-induced skeletal muscle atrophy, primarily through the induction of eIF2α phosphorylation and splicing of XBP1." (PMID 32210013, 2020). "Biological marks XBP1 and NAT1 are associated with progression and prognosis of a variety of human cancer types, but their roles in GBC remain to be identified." (PMID 32793479, 2020). "For example, XBP1 is involved in the development and progression of cancer by modulating cancer cell proliferation, apoptosis, invasion, metastasis, and drug resistance." (PMID 32793479, 2020). "To date, although the accumulation of XBP1s was reported in cancer cell lines exposed to acute and moderate hypoxia, the impairment of XBP1 splicing under acute hypoxia was also reported." (PMID 32545307, 2020).